CDK9 (cyclin dependent kinase 9)
Diseases named in the same sentence as CDK9 in open-access papers (continued):
Sharing a sentence is not in itself a finding about the gene and the disease.
breast carcinoma (continued). "Indeed, these alterations in gene expression might explain the results from a previous study demonstrating that CDK9 inhibition disrupted breast cancer stem cells." (PMID 41505030, 2026). "Consequently, CDK9 inhibition sensitizes breast cancer to endocrine therapy, CDK4/6i, and PARPi." (PMID 40949156, 2025). "CDK9 may be a good target in breast cancer due to overexpression of CDK9 in this cancer." (PMID 37111276, 2023). "Thus, a CDK9 inhibitor in combination with the AKT inhibitor, LY294002, or the proteasome inhibitor, MG-132, may provide a potentially therapeutic strategy to enhance the sensitivity of breast cancer cells to CDK9 inhibition." (PMID 37537243, 2023). "However, our findings of improved survival after 3 years suggest that, with further validation, CDK9 expression could have a future role as a prognostic biomarker for patients with breast cancer who fail to achieve a pathologic complete response after NACT." (PMID 30405916, 2018). "The involvement of CDK7 and CDK9 revealed here in regulating H1.4-S187 phosphorylation may contribute to the unique requirement of H1.4 among H1.0 and H1.1-H1.5 for the viability of human breast cancer cells." (PMID 28539972, 2017). "Our study demonstrates that CDK9 is an effective therapeutic target against TNBC, an aggressive subtype of breast cancer for which currently limited treatment options are available." (PMID 41505030, 2026). "The crucial roles of CDK9 in T-R conflicts and DNA damage, leading to genomic instability, prompted us to investigate the efficacy of AZD4573 in breast cancer." (PMID 40713627, 2025). "We also showed successful HSMCB PRIMAB tracking with CDK-9 inhibitor and with MCL-1 mimetic in breast cancer xenograft." (PMID 40507334, 2025). "The linker was designed to favor productive ternary complex formation between CDK9, PROTAC, and CRBN, thus allowing for both efficient target binding and degradation in ER+ breast cancer cells." (PMID 41362117, 2025). "Due to the important roles of CDK9 in malignancies, we found that the CDK9 inhibitor, DRB, also induced apoptotic death through rapid depletion of Mcl-1 in MCF-7 breast cancer cells and exerted a protective effect." (PMID 37537243, 2023). "MDM2 ligase coupled with inhibitors of the targets BCL2, BRD4, CDK9, PLK1 and MCL1 in stomach tumor, and MDM2 with PIK3C3 inhibitors in breast cancer, seems to be the best therapeutic strategy." (PMID 35249548, 2022). "MDM2 ligase, coupled with inhibitors of the targets BCL2L1, BRD4, CDK9, PLK1 and MCL1 in stomach cancer, and MDM2 with PIK3C3 inhibitors in breast cancer seemed to be the best therapeutic construction." (PMID 35249548, 2022). "A large number of factors were discovered that bind within 10,000 bases of the ACBD3 transcription start site across all tissues, and some of these stand out as having roles in breast cancers, including NOTCH1-NICD, CDK9, CTCF, and CEBPB." (PMID 36012147, 2022). "In 2019, the imidazo[1,2-a]pyrazines 9 and 10 were identified by virtual screening from natural resources as CDK9 inhibitors with IC50 values of 7.88 and 5.12 μM, respectively, and evaluated as anticancer agents against breast cancer." (PMID 35890157, 2022). "These roles are reinforced by the induction of apoptosis and inhibition of cell growth in both hormone therapy-sensitive and -resistant ER+ breast cancer cell lines (e.g., MCF-7) as a consequence of CDK9 inhibition by biological or pharmacological means." (PMID 34041038, 2021). "The results revealed that the mRNA expression of CDK7, CDK8, CDK9, CDK10, CDK12, CDK19, and CDK20 was upregulated in patients with breast cancer." (PMID 33686962, 2021). "Currently, the safety and pharmacology of the CDK2/9 dual-target inhibitor Fadraciclib (NCT04983810), as well as selective CDK9 inhibitors KB-0742 (NCT04718675) and PRT2527 (NCT05159518), are being evaluated in patients with solid tumors, including breast cancer." (PMID 40949156, 2025).
breast carcinoma (continued). "Notably, an elevated expression of TK1, CDK9, and CD44 within plasma exosomes from drug-resistant breast cancer patients correlates with therapy resistance." (PMID 38001753, 2023). "In breast cancer models, the EGFR inhibitor erlotinib displayed synergy with THZ1 and with the dual cdc7/CDK9 inhibitor PHA-767491, with more lines of evidence suggesting CDK7 and CDK9 inhibitors could sensitise resistant cancer cells to EGFR-targeted therapy." (PMID 35568739, 2022). "In this report, the expression of CDK9/10/11/12/19/20 was not significantly correlated with the prognosis of patients with breast cancer." (PMID 33686962, 2021). "CDK9 inhibitors are currently in clinical trials such as in acute myeloid leukaemia but it has never been tested in breast cancer." (PMID 36046384, 2020). "Moreover, ectopic expression of MYB was sufficient to suppress CDK9 inhibitor-mediated apoptosis, strongly supporting the notion that MYB is a critical target of these inhibitors in ER+ve breast cancer cells." (PMID 26812885, 2016). "In ER+ breast cancer cell lines, CDK9 targeting has been shown to reduce the level of MYC and MYB expression and E2-independent tumor cell proliferation but little information is available of the effectiveness of CDK9 inhibition in reducing tumor growth in vivo." (PMID 37801608, 2024). "Interestingly, targeted CDK9 inhibitors, such as voruciclib, potently induce apoptosis through MCL-1 depletion in many hematologic cell lines and in a subset of breast cancer cell lines, and have recently entered clinical trials for the treatment of hematological malignancies." (PMID 35349392, 2022). "Among all these CDKs, we focused on CDK9, as kinase inhibitors against this protein have been used to develop novel proteolysis-targeting chimeras (PROTACs), and no assessment of antitumoral activity in breast cancer has been performed with this family of agents." (PMID 35628286, 2022).
leukemia (35 papers, 2014 to 2026). A malignant (clonal) hematologic disorder, involving hematopoietic stem cells and characterized by the presence of primitive or atypical myeloid or lymphoid cells in the bone marrow and the blood. "Notably, the loss of INTS6 disrupts the recruitment of PP2A to CDK9 in leukemia and unspecified solid tumors, resulting in sustained CDK9 activity and resistance to CDK9 inhibitors." (PMID 41020855, 2025). "Impaired survival associated with low CDK9 expression, may be correlated with increased MCL1 expression since increased MCL1 expression has been demonstrated to be associated with CDK9 drug resistance in leukemia, although this has to be further evaluated in a larger cohort of patients." (PMID 32012890, 2020). "In summary, the results from our in vivo experiments were consistent with those from our in vitro experiments, both showing that CDK9 knockdown had an antitumor effect on leukemia." (PMID 39800696, 2025). "Overall, these results indicated that CDDD11-8 is most likely to induce apoptosis in the leukemia cell lines by modulating the cellular activity of CDK9 and FLT3." (PMID 35267421, 2022). "An agent from these patents has progressed into clinical trials (BAY-1251152, 7) for treatment of leukaemia, as described in the “CDK9 clinical applications” section." (PMID 33632038, 2021). "Many of the pre- and clinical studies with the CDK9 inhibitors have also been undertaken towards patients with different forms of leukemia." (PMID 34062779, 2021). "An agent from this patent has progressed into clinical trials (atuveciclib, BAY-1143572, 8) for treatment of leukaemia, as described in the “CDK9 clinical applications” section." (PMID 33632038, 2021). "Next, MYB mRNA levels were measured in both MOLM13 and murine MLL-AF9 leukaemia cells following treatment with each CDK9 inhibitor." (PMID 31882723, 2019). "For instance, dinaciclib is an inhibitor of CDK1, CDK2, CDK5, and CDK9, and is active in a broad range of cancer cell lines originating from leukemia, melanoma, osteosarcoma and pancreatic cancer." (PMID 31446060, 2019). "The efficacy of the CDK9 inhibitor (part of the pTEFb complex) Flavopiridol on MLL-r leukemia cells has long been recognized." (PMID 28232907, 2017). "Our data provide the first direct evidence that specific cdk9 inhibition can alter the survival characteristics of both an immortalized leukemia cell line and primary leukemia cells derived from patients." (PMID 24495868, 2014). "Additionally, we observed that CDK9 knockdown had an antitumor effect by inhibiting U937-Luc cell proliferation in the liver, bone marrow, and spleen in a leukemia mouse model." (PMID 39800696, 2025). "In addition to HIV treatment, CDK9 inhibitors are promising therapeutics against cancers and leukemia, with specific features that target transcriptional elongation in malignant cells and viral transcription in HIV-infected cells [,38]." (PMID 40230495, 2025). "CDK9 and P-TEFb have also emerged as candidate targets in cancer and leukemia because of their critical role in regulating gene expression, and it has been suggested that CDK9 also reactivates tumor suppressor genes and is involved in promoting and maintaining cancer cell growth." (PMID 36378653, 2022). "Flavopiridol is an inhibitor of cyclin-dependent kinases (CDKs) (including CDK1, CDK2, CDK4, CDK5, CDK6, CDK7, CDK8, and CDK9) and has been investigated for the treatment of several types of cancers, including leukemia, liver cancer, and renal cancer, in clinical phase 2 trials (24, –, 26)." (PMID 31822599, 2019).
leukemia (continued). "Inhibiting CDK9 or CDK12/13 induced the rapid downregulation of the short-lived, anti-apoptotic Bcl-2 proteins Mcl1 and A1/Bfl1 in Jurkat leukemia cells and SUDHL1 lymphoma cells, whereas the expression of Bcl-2 and Bcl-xL remained unaffected." (PMID 42204137, 2026). "Even more, in leukemia and lymphoma cells, SIRT2 was found to induce STAT1 phosphorylation at serine 727 by deacetylating cyclin-dependent kinase 9 (CDK9) in a Type I IFN-dependent manner." (PMID 34571733, 2021). "Although murine leukemia cells (BCR-ABL1p185+) contain high levels of CDK6, CDK7, CDK8, CDK9, and CDK19, knockdown of CDK6, CDK7, CDK9, or CDK19 has little effect on cell survival and proliferation in an inducible system." (PMID 31628323, 2019). "RNase digestion-coupled IP and co-IP revealed a direct interaction between hnRNPK and CDK9/P-TEFb and indirect interactions between hnRNPK and CDK7/TFIIH as well as RNA-pol-II CTD-S2P in the OCI-M2 leukaemia cells." (PMID 29563491, 2018). "Dinaciclib, which inhibits the CDK9 component of pTEFb, showed efficacy in preclinical models both in vitro and in vivo, inducing apoptotic cell death in MLL-r leukemia models and inhibition of MLL target genes." (PMID 28232907, 2017). "Here we present direct evidence that cdk9 is important for cancer cell survival and describe the characterization of the potent cdk9 inhibitor CDKI-73 in primary human leukemia cells." (PMID 24495868, 2014). "Most frequent MLL1-fusion partners AF4/AFF4, AF9/ENL and ELL, together with CDK9/cyclin-T1, constitute super elongation complexes (SEC), which promote aberrant gene transcription, oncogenesis and maintenance of MLL1-rearranged (MLL1-r) leukemia." (PMID 35395864, 2022). "Similarly, the inhibitor of cyclin-dependent kinase 9 (CDK9) induced AML apoptosis by down-regulating the expression of MCL1 and demonstrated anti-leukemia and clinical activity in refractory and relapsed (R/R) AML." (PMID 35865470, 2022). "Western blotting demonstrated a small increase (~1–2 fold) in the expression of total RNA-pol-II, CTD-S2P, CDK7, CDK9/P-TEFb, BRD4 and BRD2 in the 5-AZA-resistant M2AR and SCAR leukaemia cells compared to the original 5-AZA-sensitive OCI-M2 and SC leukaemia cells." (PMID 29563491, 2018). "At the same time RNAPII CTD S2 and MCL1, which are strongly dependent on the activity of CDK9 in leukemia cells, were not affected." (PMID 28422713, 2017). "Since we showed above that CDK9 is essential for MLL-AF9- and MLL-ENL-driven MYB transcription in reporter assays and that it is recruited to MYB by the MLL-AF9 protein, we wished to investigate the effect of CDK9 inhibitors on MYB transcription, particularly in MLL-fusion driven leukaemia cells." (PMID 31882723, 2019).
acute myeloid leukemia (25 papers, 2014 to 2026). Acute myeloid leukemia (AML) is a group of neoplasms arising from precursor cells committed to the myeloid cell-line differentiation. "In acute myeloid leukemia cell lines, venetoclax combined with alvocidib (CDK9 inhibitor) reduced cell viability while reducing Mcl-1 levels." (PMID 40704654, 2025). "KB-0742 is a CDK9 inhibitor with a narrower inhibitory profile and pre-clinical efficacy in prostate cancer and acute myeloid leukemia (AML)." (PMID 36376377, 2023). "PROTAC B03 induced CDK9 degradation in vivo in mouse models of acute myeloid leukemia (AML,) and showed acceptable pharmacokinetic properties with a plasma half-life of more than 1.3h after a single intravenous injection of 5 mg/kg." (PMID 36986673, 2023). "BAY1143572 (atuveciclib), the first highly selective CDK9 inhibitor described by Bayer, exhibited marked tumour growth inhibition in preclinical models of acute myeloid leukaemia and adult T-cell leukaemia/lymphoma." (PMID 35568739, 2022). "CDK9 inhibitors are being tested for the treatment of multiple malignancies, including multiple myeloma, acute myeloid leukemia, prostate cancer, and hepatocellular carcinoma, making CDK9 a valid potential therapeutic target and a novel prognostic marker." (PMID 35326643, 2022). "It was the lead degrader of further development and CDK9 degradation was a potentially valuable treatment strategy for acute myeloid leukemia." (PMID 35680848, 2022). "Cyclin-dependent kinase 9 inhibitor (CDK9i) effectively attenuates acute myeloid leukemia and chronic lymphoblastic leukemia by inducing apoptosis and inhibiting cell proliferation." (PMID 33748130, 2021). "As part of a medicinal chemistry and drug discovery program, we identified CDDD11-8 as a potent, orally bioavailable CDK9 inhibitor selective for CDK9 (with >50-fold selectivity over other CDKs assessed) that reduced in vitro and in vivo growth of human cell line models of acute myeloid leukaemia." (PMID 38001268, 2024). "CDK9 inhibitors have a significant inhibitory effect on acute myeloid leukemia (AML) and chronic lymphocytic leukemia (CLL)." (PMID 33748130, 2021). "A variety of hematological malignancies, including acute myeloid leukemia (AML), multiple myeloma (MM), and diffuse large B-cell lymphoma (DLBCL), have been associated with dysregulated CDK9 activity, which sustains oncogene expression and contributes to resistance to treatment." (PMID 42201387, 2026). "Regarding combination therapies, the CDK9 inhibitor dinaciclib and panobinostat together induce apoptosis over the short-term in MLL-AF9-driven acute myeloid leukemia (AML)." (PMID 33117804, 2020).
lymphoma (25 papers, 2013 to 2026). A malignant (clonal) proliferation of B- lymphocytes or T- lymphocytes which involves the lymph nodes, bone marrow and/or extranodal sites. "Despite PRs observed in PTCL and HGBCL‐DH‐BCL2, the median duration of response was only 3.5 months, which is consistent with other studies of CDK9 inhibition in R/R lymphomas." (PMID 41169010, 2026). "CDK9 inhibitors have shown activity in relapsed or refractory (R/R) lymphomas; however, durable remissions are observed in a minority of patients." (PMID 41169010, 2026). "Inhibition of the PIM3 kinase pathway has been shown to inhibit TNBC by indirectly targeting MYC and to enhance response to a CDK9 inhibitor in models of lymphoma." (PMID 38001268, 2024). "This study demonstrates the biologic advantage of a selective CDK9 inhibitor for the treatment of MYC+ lymphoma preclinical models which is confirmed by analysis of blood samples from patients treated with 30 mg enitociclib i.v. once weekly." (PMID 37882668, 2023). "The CDK9 inhibitor AZD4573 was also found to indirectly down-regulate BFL-1 in conjunction with MCL-1 in BH3-mimetic–resistant lymphoma cell lines and lead to in vivo tumour regressions in BFL-1+ DLBCL PDX models." (PMID 35900226, 2022). "Investigation of Dinaciclib-mediated inhibition of CDK9 in aggressive MYC-induced lymphomas demonstrated the remarkable effectiveness of CDK9 inhibitors." (PMID 34372899, 2021). "Flavopiridol is a CDK inhibitor, with high selectivity for CDK9, used in phase II clinical trial for the treatment of relapsed/refractory lymphoma or multiple myeloma." (PMID 32412527, 2020). "For the first time, we also demonstrated that high concentration metformin increased sensitivity of lymphoma cells to the CDK9 inhibitor, BAY-1143572 with potentiating effects in the mantle cell line Jeko-1 of particular interest." (PMID 29765528, 2018). "Recently, direct in vivo cytotoxicity of the selective CDK9 inhibitor BAY1143572 against malignant T cells (adult T cell leukemia/lymphoma, ATL) was shown." (PMID 29899864, 2018). "Overexpression of CDK9 and cyclin T1 has been reported in B and T cell precursor-derived lymphomas, anaplastic large T cell lymphoma, and follicular lymphomas, while strong nuclear staining of these proteins has been described in classical Hodgkin’s lymphoma." (PMID 25625291, 2015). "For relative comparison, MYC does not rank in the top DEGs of this study, but the extent of downregulation (−17.108-fold change) is greater than the novel DEGs identified further strengthening the utility of selective CDK9 inhibitors for targeting MYC+ lymphomas." (PMID 37882668, 2023). "A high RIS score was also reported for the positive regulation of the reactive oxygen species (ROS) metabolic process pathway (GO:2000379) associated with the DB cell line (lymphoma) when administered with Dinaciclib (an inhibitor of CDK1, CDK2, CDK5, and CDK9)." (PMID 37432499, 2023). "Also known as alvociclib, this wide spectrum CDK inhibitor targets CDK1, CDK2, CDK4, CDK6, CDK7 and CDK9 and displays antiproliferative efficacy in several solid tumours and sarcomas, as well as in leukaemia, lymphoma and multiple myeloma." (PMID 25625291, 2015). "Furthermore, deregulations in the CDK9-related pathway were reported in a number of human malignancies, such as lymphomas, neuroblastoma, primary neuroectodermal tumor, rhabdomyosarcoma, and prostate cancer." (PMID 23840966, 2013). "An imbalance of expression levels between CDK9 and CCNT1 has been found in several lymphoma types, suggesting a common mechanism of deregulation of transcription in the neoplastic transformation of these cells." (PMID 37756103, 2023).